SARM1 (sterile alpha and TIR motif containing 1)
Diseases named in the same sentence as SARM1 in open-access papers (continued):
Sharing a sentence is not in itself a finding about the gene and the disease.
peripheral neuropathy (continued). "Further exploration of the Sarm1 signaling pathway in neurodegeneration is warranted given the ability of Sarm1KO to attenuate axon loss and improve behavioral outcomes in models of Traumatic Brain Injury (TBI) and peripheral neuropathy." (PMID 30010873, 2018). "On the other hand, small molecules inhibiting SARM1 promote the rescue of damaged axons that would otherwise degenerate, and inhibiting SARM1 pharmacologically might protect axon organization and function in paclitaxel-induced peripheral neuropathy." (PMID 37781093, 2023). "Through its inhibition of NAD+-cleavage activity, carnosol inhibits SARM1-dependent cell death and axonal degeneration, reducing vincristine (VCR)-induced pain and peripheral neuropathy symptoms in vivo." (PMID 40722912, 2025). "To confirm the neuroprotective effect of carnosol via SARM1 in vivo, we performed an analysis using a VCR-induced peripheral neuropathy model." (PMID 40722912, 2025). "For instance, if Sarm1 knockout in only PNS neurons produced a rescue effect similar to the constitutive Sarm1 knockouts, then it would strongly suggest that peripheral neuropathy does indeed precede CNS toxicity." (PMID 41419972, 2025). "Young SARM1 knockout mice do not have any obvious phenotype and furthermore display normal exercise performance, but the loss of SARM1 prevents neuron degeneration in models of spinal cord injury, traumatic brain injury, peripheral neuropathy, and retinal degenerative diseases." (PMID 37307837, 2024). "Symptoms of pain and peripheral neuropathy tend to increase with age; the decrease in NAD+ levels due to activation of SARM1 may be involved in these symptoms." (PMID 40722912, 2025). "We investigated vincristine-mediated brain toxicity in young mice lacking Sarm1, a gene whose deletion protects against vincristine-induced peripheral neuropathy." (PMID 41419972, 2025). "Sarm1 knockout is sufficient to protect nerve axon structure and function in animal models of traumatic axonal injury; chemotherapy-induced, inflammatory, and CMT2A models of peripheral neuropathy; as well as mouse models of both T1D- and T2D-associated DPN." (PMID 38175722, 2024). "Sarm1 knockout mice are viable and without apparent phenotypes under routine conditions, but are protected against neurodegeneration in models of axotomy, traumatic brain injury, peripheral neuropathy, glaucoma, and retinal degenerative diseases." (PMID 34991663, 2022). "Furthermore, we show that neurotoxicity of cisplatin requires activation of Sarm1, a key regulator of Wallerian degeneration, as mice lacking the Sarm1 gene do not develop peripheral neuropathy as evaluated by both behavioral or pathological measures." (PMID 33318563, 2020). "In addition, SARM1 inhibitors are currently under clinical development for treatment of neurodegenerative conditions, including multiple sclerosis, amyotrophic lateral sclerosis, Parkinson’s disease, optic neuropathies, DPN, and chemotherapy-induced peripheral neuropathy." (PMID 38175722, 2024).
tumor (16 papers, 2017 to 2025). "We next examined whether axonal injury in WM-dense regions has a causative role in tumour progression and, if so, whether this depends on WD and could be reversed by SARM1 inactivation." (PMID 40836081, 2025). "Second, given the prolonged preservation of axonal integrity that we observed in Sarm1−/− tumours, we assessed neurological function in mice with advanced tumours (corresponding to ≤2 weeks before death) using motor score testing." (PMID 40836081, 2025). "The same states were also found in tumours in Sarm1−/− mice, but in different proportions, with a particularly marked increase in NPC-like cells and a reduction in MES-like cells." (PMID 40836081, 2025). "npp tumours were induced in Sarm1−/− mice and the axonal integrity was examined in intermediate tumours." (PMID 40836081, 2025). "Transcriptomes from a total of 78,131 and 23,916 cells were analysed from terminal tumours in WT and Sarm1−/− mice, respectively." (PMID 40836081, 2025). "To test this more directly, we generated npp tumours in WT and Sarm1−/− mice and used H&E staining and immunofluorescence analysis to examine their phenotypes at the terminal disease stage." (PMID 40836081, 2025). "By contrast, TAMs in Sarm1−/− mice with tumours expressed higher levels of pro-inflammatory microglial markers characteristic of infiltrative tumour regions." (PMID 40836081, 2025). "To this end, we used genetic perturbation of the pathway by generating npp tumours in WT or congenic Sarm1−/− mice and performing functional studies." (PMID 40836081, 2025). "Although further studies are needed to identify the molecular mechanisms underlying this transcriptional relationship, our data suggest that maintaining the NMNAT2/SARM1 balance is crucial for cancer cells homeostasis and tumor biology." (PMID 40955574, 2025). "First, we compared tumour latencies in survival studies and found that Sarm1 deletion resulted in a significant extension of survival (median survival 18 weeks in WT and 21 weeks in Sarm1−/−)." (PMID 40836081, 2025). "Immune profiling of late-stage tumours by flow cytometry confirmed this result, revealing that npp tumours in WT mice were overall more immune infiltrated, containing higher proportions of macrophages and T cells, whereas microglia dominated in tumours generated in Sarm1−/− mice." (PMID 40836081, 2025). "We claim that understanding the correlation between NMNAT2 and SARM1 activity could have important therapeutic implications and represent a biomarker of tumor aggressiveness." (PMID 40955574, 2025). "Furthermore, LIANA analysis revealed that increased heterotypic signalling occurred between tumour cells and their microenvironment in the WT, relative to in Sarm1−/− mice." (PMID 40836081, 2025). "We conclude that WD represents a key driver of gliomagenesis, which could be targeted through inhibition of SARM1 to suppress tumour progression and ameliorate disease course and its symptoms." (PMID 40836081, 2025). "To test this hypothesis, we quantified the distribution of tumour cells in Sarm1−/− tumours at the intermediate stage, when WM tropism is maximal in the WT and found a complete loss of WM bias in the absence of WD." (PMID 40836081, 2025). "Notably, in Sarm1−/− mice, the tumours also appeared overall more diffuse compared with the WT controls, as judged by smaller proportions of tumours forming a defined bulk, lower tumour density and increased tumour area on the basis of both fluorescence imaging and H&E assessment." (PMID 40836081, 2025). "We show that genetic inactivation of Sarm1, the main effector of WD4, preserves axonal integrity in GBM models, thereby both suppressing tumour progression and improving neurological function." (PMID 40836081, 2025). "Consistent with this, intratumoural administration of AAV8-Syn-SARM1-CDN-eGFP (but not AAV8-Syn-eGFP) suppressed tumour cell proliferation at the intermediate tumour stage but not at the late tumour stage." (PMID 40836081, 2025).
tumor (continued). "We found that axonal transection injury increases tumour cell proliferation in both early and intermediate npp tumours in WT mice but not in Sarm1−/− mice, in which axonal degeneration was suppressed, and proliferation remained at the baseline sham levels." (PMID 40836081, 2025). "Our results confirm that lack of TLR4 and SARM1 interfere with important tumor-related characteristics such as clonogenic and migration potentials." (PMID 35468924, 2022). "Apart from CD38, SARM1 were also confirmed as the additional NAD+-depleting enzyme that using NAD+ to produce cADPR, the precise functions of cADPR in those abnormal situations including tumor progression, inflammation, and injury-induced axon death need further characterizations." (PMID 34226519, 2021). "Moreover, TLR pathway proteins such as TLR4, SARM1, and HMGB1 may play additional roles related to tumor development." (PMID 29472602, 2018).
neurological diseases (13 papers, 2014 to 2025). "Since SARM1 mutations have been identified in human neurological disease, SARM1 inhibition has become an attractive therapeutic strategy to preserve axons in a variety of disorders of the peripheral (PNS) and central nervous system (CNS)." (PMID 37091921, 2023). "This should also facilitate identifying other potential links between SARM1 variant alleles and other neurological disorders where SARM1 is predicted to play an important role." (PMID 35974060, 2022). "Since inhibition of SARM1 function is being proposed to treat neurological disease, it is crucial to identify whether loss of SARM1 leads to any disruption of vertebrate CNS or PNS myelination in a cell autonomous or non-cell autonomous fashion." (PMID 37091921, 2023). "Whether further mutations to NMNAT2, SARM1 or other proteins involved in the Wallerian degeneration pathway represent risk factors for other neurological diseases in living humans, is yet to be seen." (PMID 34307460, 2021). "The purpose of this study was to find a beneficial compound that inhibits axonal degeneration through SARM1 inhibition and alleviates the symptoms of various neurological diseases from food ingredients." (PMID 40722912, 2025). "Current efforts are focused on the development of SARM1 inhibitors for the prevention and treatment of neurologic disease." (PMID 38175722, 2024). "Axon degeneration is a pathologic feature of many neurologic disorders, and SARM1 variants have been found to be associated with ALS and other neurologic disorders." (PMID 37002660, 2024). "In summary, the method developed here is useful for investigating the mechanism of action of SARM1 in neurodegeneration with potential applications in the development of therapies for SARM1-related neurological disorders." (PMID 38398599, 2024). "Recently, the SARM1 protein has been highlighted as a promising target in multiple neurological diseases such as spinal cord injury, traumatic brain injury and sympathetic neuropathy." (PMID 35869039, 2022). "Because of the function of Sarm1 in innate immune responses, our data also reveals a potential treatment for inflammation-related neurological disorders by using mGluR agonists." (PMID 24744698, 2014). "Blocking macrophage-mediated axon elimination could be a promising therapeutic strategy for SARM1-dependent neurological diseases." (PMID 40496808, 2025). "This is important to know as it could have adverse implications for the use of therapies aimed to treat various neurological disorders through inhibition of SARM1 function." (PMID 37091921, 2023). "The discoveries of the protective Wallerian degeneration slow (WldS) and of sterile alpha and TIR motif containing 1 (SARM1) activation as the main instructive signal for WD have shed new light on the regulatory role of NAD+ in axonal degeneration in a growing number of neurological diseases." (PMID 37503611, 2023). "SARM1 responds to stress, induces axonal degeneration by hydrolyzing NAD+, and is involved in the pathological progression of various neurological diseases." (PMID 40722912, 2025). "These proposed mechanisms are not specific to CMT2A and MFN2 and suggest that SARM1 activation is a common feature of many neurological disorders with mitochondrial dysfunction." (PMID 36287202, 2022). "Neurological disease from LACV is the result of neuronal damage and cell death, and this damage is mediated by sterile alpha and TIR-containing motif 1 (SARM1), a MyD88-related protein expressed at high levels in neurons and associated with multiple forms of neuronal death." (PMID 31470541, 2019). "Thus, strategies to inhibit SARM1 function to treat neurological disease are unlikely to perturb myelination in humans." (PMID 37091921, 2023).
cancer (9 papers, 2015 to 2025). A tumor composed of atypical neoplastic, often pleomorphic cells that invade other tissues. "Remarkably, we also report that the sensitivity of cancer cells to Vacor toxicity is restricted to those lines expressing high levels of SARM1, thereby indicating that Coleman's claim that SARM1 is causative of Vacor neurotoxicity can also be applied to cancer cells." (PMID 40955574, 2025). "Overall, our study underscores the pivotal role of SARM1 in Vacor‐induced cytotoxicity in cancer cells, as well as its potential as an antineoplastic agent to design innovative avenues for cancer therapy." (PMID 40955574, 2025). "A key finding of the present study is that cancer cell lines expressing SARM1 also exhibit high levels of NMNAT2." (PMID 40955574, 2025). "Purified carnosol inhibited the enzymatic activity of SARM1 and suppressed neurite degeneration and cell death induced by the anti-cancer medicine vincristine (VCR)." (PMID 40722912, 2025). "Further, we report that cancer cells sense the abnormal expression of SARM1 and readily induce the expression of NMNAT2." (PMID 40955574, 2025). "We next assessed the expression levels of SARM1 in various Vacor‐sensitive and ‐insensitive cancer cell lines." (PMID 40955574, 2025). "Data suggest that the correlation between NMNAT2 and SARM1 expression levels observed in mammalian axons also occurs in cancer cells." (PMID 40955574, 2025). "Based on radiosensitization of cancer therapy depending on autophagy, we proposed that Sarm1-mtKR mediates ROS production on mitochondria, furthermore inducing mitochondrial dysfunction, autophagic death, and proliferation inhibition." (PMID 34306311, 2021). "To test this idea, we treated wild type and Sarm1-mutant zebrafish with several chemical compounds that are under clinical trials or used as first-line treatment for common cancers in humans." (PMID 32001778, 2020). "Of note, while SARM1 is highly expressed in neurons, its expression levels and role in cancer cells remain unknown." (PMID 40955574, 2025). "It remains to be addressed, therefore, whether SARM1 activation contributes to Vacor cytotoxicity also in cancer cells." (PMID 40955574, 2025). "For the first time, our study shows that SARM1 expression varies among different cancer cell lines." (PMID 40955574, 2025). "Smoldering SARM1 activation levels might indeed influence both cancer cell survival and proliferation, as well as correlate with the development and prognosis of malignant tumors." (PMID 40955574, 2025). "On the other hand, given the antitumor potential of Vacor‐like molecules, it is important to clarify whether SARM1 plays a role in cancer cells and to define the role of NMNAT2 in SARM1‐dependent Vacor‐induced cell death." (PMID 40955574, 2025). "Whether a similar functional interaction between NMNAT2 and SARM1 exists in cancer cells remains unknown." (PMID 40955574, 2025). "Overall, data show a key role of SARM1 in Vacor‐induced NAD depletion and death in cancer cell lines." (PMID 40955574, 2025). "Based on these considerations, this study aimed to investigate the contribution of NMNAT2 and SARM1 to Vacor‐induced NAD depletion and cell death in cancer cell lines." (PMID 40955574, 2025). "In other words, NMNAT2 expression could negatively regulate SARM1 activation via modulation of NAD metabolism, thereby creating a feedback loop also in cancer cells." (PMID 40955574, 2025).
bacterial infections (3 papers, 2022 to 2025). "Accordingly, C. elegans with genetic mutations that specifically block either multimerization or the NAD+ glycohydrolase activity of TIR-1/SARM1 fail to induce p38 PMK phosphorylation, are unable to increase immune effector expression, and are dramatically susceptible to bacterial infection." (PMID 35098926, 2022). "In vitro biochemical studies of purified protein and C. elegans genetic analyses revealed that multimerization and a phase transition of TIR-1/SARM1 engages its NADase activity to activate the p38 PMK-1 innate immune pathway and provide protection during bacterial infection." (PMID 35098926, 2022).
metabolic disease (3 papers, 2024 to 2026). A congenital disorder (due to inherited enzyme abnormality) or acquired (due to failure of a metabolically important organ) disorder resulting from an abnormal metabolic process. "Rescue of bone health by Sarm1 knockout is due to sustained osteoblast function and abrogated local oxidative stress responses, even in settings of severe metabolic disease." (PMID 38175722, 2024). "Like CD38, SARM1 expression or activity may increase in ageing or metabolic disease and SARM1 could also be involved in pathologies related to NAD+ decline." (PMID 38176648, 2024).
central nervous system diseases (1 paper, 2025). "The role of SARM1 in central nervous system diseases, particularly acute injury, has been increasingly recognized." (PMID 41272776, 2025).
inflammation (1 paper, 2020). Aberrant reaction of the microcirculation characterized by movement of fluid and leukocytes from the blood into extravascular tissues. "In conclusion, Sarm1 deletion delayed axonal degeneration early in the course of CNS inflammation, but did not confer long-term protection from axonal degeneration in an animal model of immune-mediated CNS inflammation." (PMID 32584865, 2020).
retinopathies (1 paper, 2020). "Since the SARM1 pathway is likely druggable, these findings provide a framework for developing new therapeutic strategies for treating patients with LCA9 and potentially other retinal disorders." (PMID 33107823, 2020).
skeletal disease (1 paper, 2024). "In this study, we used global and conditional knockout models of sterile-α and TIR-motif-containing protein-1 (Sarm1) to isolate the role of DPN in the onset of T1D skeletal disease." (PMID 38175722, 2024). "Thus, in addition to clarifying the mechanistic relationship between DPN and skeletal disease in vivo, we believe our results can inform the future use of SARM1 inhibitors as a novel strategy to promote diabetic neuroskeletal health." (PMID 38175722, 2024). "In this study, we isolated the role of DPN in skeletal disease with global and conditional knockout models of sterile-α and TIR-motif-containing protein-1 (Sarm1)." (PMID 38175722, 2024). "If true, we may expect SARM1 inhibitors to perform well in humans regardless of sex, as diabetic skeletal disease emerges at much lower levels of glycemia in humans." (PMID 38175722, 2024).
SARM1 also shares sentences with these, for which no sentence is quoted: Cognitive impairment (3 papers); rheumatoid arthritis (3); frontotemporal dementia (2); hereditary spastic paraplegia (2); lung fibrosis (2); motor neuron disorder (2); Parkinson’s (2); polyneuropathies (2); X-linked juvenile retinoschisis (2); age-related macular degeneration (1); anxiety disorder (1); Bunyavirus infection (1); cardiovascular disease (1); Cerebral atrophy (1); Cerebral ischemia (1); Charcot-Marie-Tooth disease type (1); colorectal cancer (1); depression (1); encephalitis (1); fungal infections (1); gastric cancer (1); inflammatory bowel disease (1); influenza infection (1); leukemia (1); liver cancer (1); lung carcinoma (1); lung squamous cell carcinoma (1); memory impairment (1); myocarditis (1); optic neuritis (1).
A further 10 diseases each share a sentence with SARM1 in 1 paper.